PDLIM4 (PDZ and LIM domain 4)
Description:
[Isoform 1]: Suppresses SRC activation by recognizing and binding to active SRC and facilitating PTPN13-mediated dephosphorylation of SRC 'Tyr-419' leading to its inactivation. Inactivated SRC dissociates from this protein allowing the initiation of a new SRC inactivation cycle. Involved in reorganization of the actin cytoskeleton. In nonmuscle cells, binds to ACTN1 (alpha-actinin-1), increases the affinity of ACTN1 to F-actin (filamentous actin), and promotes formation of actin stress fibers. Involved in regulation of the synaptic AMPA receptor transport in dendritic spines of hippocampal pyramidal neurons directing the receptors toward an insertion at the postsynaptic membrane. Links endosomal surface-internalized GRIA1-containing AMPA receptors to the alpha-actinin/actin cytoskeleton. Increases AMPA receptor-mediated excitatory postsynaptic currents in neurons (By similarity). [Isoform 2]: Involved in reorganization of the actin cytoskeleton and in regulation of cell migration. In response to oxidative stress, binds to NQO1, which stabilizes it and protects it from ubiquitin-independent degradation by the core 20S proteasome. Stabilized protein is able to heterodimerize with isoform 1 changing the subcellular location of it from cytoskeleton and nuclei to cytosol, leading to loss of isoforms 1 ability to induce formation of actin stress fibers. Counteracts the effects produced by isoform 1 on organization of actin cytoskeleton and cell motility to fine-tune actin cytoskeleton rearrangement and to attenuate cell migration.
Synonyms: RIL
Tractability: Antibody: its Gene Ontology location is reachable by antibodies, with high confidence; UniProt places it where antibodies can reach, with medium confidence. PROTAC: ubiquitination databases record sites on it; its protein half-life has been measured.
Gene: Protein-coding gene on chromosome 5 (132,257,644 to 132,273,454, forward strand). Ensembl gene ENSG00000131435.
Subcellular location: Cytoplasm, cytoskeleton (Isoform 1); Nucleus; Cytoplasm; Cytoplasm, perinuclear region; Cell projection, lamellipodium; Cell projection, dendritic spine; Early endosome membrane; Recycling endosome membrane; Synapse, synaptosome; Cytoplasm (Isoform 2)
Subcellular location (Human Protein Atlas): Actin filaments; Cytosol; Plasma membrane
Gene Ontology:
Molecular function: alpha-actinin binding; protein binding; protein homodimerization activity; protein phosphatase binding; actin binding; muscle alpha-actinin binding
Biological process: actin cytoskeleton organization; excitatory chemical synaptic transmission; heart development; muscle structure development
Cellular component: actin cytoskeleton; cytoplasm; cytoskeleton; cytosol; filamentous actin; lamellipodium; nucleus; perinuclear region of cytoplasm; stress fiber; adherens junction; dendritic spine; early endosome lumen; postsynaptic membrane; recycling endosome lumen; Z disc; early endosome membrane; recycling endosome membrane; synapse
Genetic constraint (gnomAD): Loss-of-function variants: 15 observed, 24.16 expected, observed/expected ratio (o/e) 0.62, 90% interval 0.41 to 0.96. The upper end of that interval is the gene's LOEUF score, 0.96, which puts it in group 4 of 6, group 1 being the genes least tolerant of losing a copy. Missense variants: 400 observed, 412.09 expected, observed/expected ratio (o/e) 0.97, 90% interval 0.89 to 1.05. Synonymous variants: 158 observed, 171.96 expected, observed/expected ratio (o/e) 0.92, 90% interval 0.81 to 1.05.
Homologues: Orthologues: chimpanzee PDLIM4 (100% identical), macaque PDLIM4 (98% identical), mouse Pdlim4 (91% identical), pig PDLIM4 (90% identical), rat Pdlim4 (90% identical), guinea pig PDLIM4 (79% identical), rabbit PDLIM4 (63% identical), dog PDLIM4 (55% identical), zebrafish pdlim4 (50% identical), tropical clawed frog pdlim4 (45% identical). Paralogues in human: PDLIM1 (45% identical), PDLIM3 (42% identical), PDLIM2 (34% identical), LDB3 (32% identical), PDLIM5 (28% identical), PDLIM7 (27% identical), PRICKLE4 (15% identical).
Diseases named in the same sentence as PDLIM4 in open-access papers:
PDLIM4 is named in the same sentence as 31 diseases in open-access papers, as found by Europe PMC text mining. Sharing a sentence is not in itself a finding about the gene and the disease. The quoted sentences say what the papers report.
prostate carcinoma (6 papers, 2011 to 2023). A carcinoma that arises from epithelial cells of the prostate gland. "A significant down-regulation of PDLIM4 expression has been well described in prostate cancer, and the hypermethylation of the PDLIM4 gene is considered to be associated with the down-regulation." (PMID 30578378, 2019). "PDZ and LIM domain 4 (PDLIM4), also known as RIL, is thought to be a suppressor of ovarian, breast and prostate cancers, and its low expression has been associated with hypermethylation in both primary BRCA and lymph node metastases." (PMID 38235137, 2023). "PDLIM4, an actin-binding protein containing PDZ and LIM domains, has been implicated as a tumor suppressor in prostate cancer and ovarian cancer due to its hypermethylation or downregulation feature." (PMID 38159261, 2023). "In prostate cancer cells, both PDLIM4 mRNA and protein expression are reduced by hypermethylation of the gene." (PMID 24213111, 2011). "PDLIM4 may act as a tumor suppressor in prostate cancer by controlling cell proliferation and also may predict recurrence." (PMID 24213111, 2011). "PDLIM4 was found hypermethylated and silenced in prostate cancer." (PMID 21760961, 2011).
breast carcinoma (5 papers, 2019 to 2024). "In breast cancer cells, the PDLIM4 gene encodes an adaptor protein that functions as a key regulator of stress fibre assembly, actin cytoskeleton remodelling, and epithelial–mesenchymal transition." (PMID 36936167, 2023). "Initially, univariate Cox regression analysis revealed that 12 genes were associated with the prognosis of breast cancer, followed by LASSO analysis to derive a prognostic signature composed of 8 genes, including CERCAM, EMP1, SDC1, PRKG1, XG, TNN, WLS, and PDLIM4." (PMID 38728370, 2024). "Seven of the 15 TME prognostic genes (NOS2, SCG2, RGS3, EMP1, PDLIM4, PCDH9, and GFI1) were involved in enhancing cell proliferation, destroying cell apoptosis, promoting cell invasion, or migration in breast cancer." (PMID 36936167, 2023). "As expected, seven of the TME prognostic genes (NOS2, SCG2, RGS3, EMP1, PDLIM4, PCDH9, and GFI1) showed dual functions in breast cancer progression." (PMID 36936167, 2023). "The LIM-homeodomain TFs, reversion-induced Lim (RIL) or PDZ and LIM domain 4 (PDLIM4), promote apoptosis in cancer cells and, hence, are silenced epigenetically in AML and MDS, as well as breast cancer." (PMID 31614829, 2019).
ovarian carcinoma (5 papers, 2022 to 2025). A malignant neoplasm originating from the surface ovarian epithelium. "Similarly, PDLIM4 is associated with poor prognosis in ovarian cancer by inhibiting tumor invasion through the suppression of STAT3 signaling." (PMID 40243891, 2025). "Notably, the PDLIM family comprises 10 members, several of which—including PDLIM250 and PDLIM4—have been linked to ovarian cancer progression via mechanisms such as the STAT3 signalling pathway." (PMID 40697100, 2025). "Multiple LIM domain genes, such as LMX1B and PDLIM4 contributed to the tumorigenesis of ovarian cancer." (PMID 36338962, 2022). "The down-regulation of PDLIM4 (PDZ and LIM domain 4) was shown to be correlated with short overall survival of ovarian cancer patients." (PMID 36338962, 2022).
glioma (3 papers, 2013 to 2023). A benign or malignant brain and spinal cord tumor that arises from glial cells (astrocytes, oligodendrocytes, ependymal cells). "PDLIM4 had been identified as a gene signature associated with the clinical outcome in high-grade gliomas." (PMID 32047515, 2019). "However, it could be significantly upregulated in GBM cells along with other genes in high-grade gliomas, suggesting that PDLIM4 may have a potential oncogenic function." (PMID 38159261, 2023). "Previous studies have reported the involvement of PDIA4, MXRA8, PDLIM4, C9orf64, and GZMB in glioma patients’ poor prognosis through bioinformatics analysis." (PMID 38159261, 2023). "The expression of EDNRB, HJURP and PDLIM4 genes were significantly different between glioblastomas and grade III gliomas (p<0.001, p=0.004 and p<0.001, respectively)." (PMID 24039914, 2013).
thyroid cancer (3 papers, 2015 to 2023). "Two of the 18 BRAFV600E-specific genes are believed to be tumor suppressor genes: PDLIM4 and IQGAP2, both previously related to thyroid cancer." (PMID 26625260, 2015).
asthma (2 papers, 2023 to 2025). "Using this framework, one study nominated IL1R1(Interleukin 1 Receptor Type 1), ECM1(Extracellular Matrix Protein 1), and PDLIM4 (PDZ and LIM Domain Protein 4) as causal asthma targets, with additional signals implicating ECM1 in neuro-immune pathways." (PMID 41459491, 2025). "In the brain, per 10-fold increase in ECM1 (OR, 1.05; 95% CI, 1.03–1.08) and PDLIM4 (OR, 1.05; 95% CI, 1.04–1.07) increased the risk of asthma." (PMID 37809092, 2023). "For example, increasing PDLIM4 increased the risk of asthma (OR = 1.41; 95% CI, 1.22–1.63; P = 2.39 × 10−6) in the FinnGen cohort." (PMID 37809092, 2023). "The findings of this study were replicated in different datasets, indicating that IL1R and PDLIM4 are associated with asthma." (PMID 37809092, 2023). "PhenoScanner also revealed that C1QTNF5 is associated with rs3900945 but in a trans-acting manner, rendering them less likely to bias the PDLIM4–asthma association." (PMID 37809092, 2023). "Additionally, IL1R1 and PDLIM4 were found to be associated with asthma in two other large asthma GWAS datasets, further supporting the reliability of the potential drug targets identified in this study." (PMID 37809092, 2023). "Our integrative analysis revealed that asthma risk is causally affected by the levels of IL1R1, ECM1, and PDLIM4." (PMID 37809092, 2023). "Our study demonstrates a causal relationship between genetically determined IL1R1, ECM1, and PDLIM4 plasma protein levels and asthma and, additionally, a causal relationship between ECM1 protein levels in brain tissue representing neurogenic inflammation and asthma." (PMID 37809092, 2023). "Therefore, we posit that PDLIM4 may hold promise as a therapeutic target for treating asthma." (PMID 37809092, 2023). "Although our PPI analysis did not reveal any interactions between PDLIM4 and current asthma medications, our study validated PDLIM4 as a potential drug target for asthma through external validation in two separate cohorts." (PMID 37809092, 2023). "The study identified three potential drug targets for asthma, including IL1R1, ECM1, and PDLIM4." (PMID 37809092, 2023). "Therefore, the possibility that carnitine affects the relationship between PDLIM4 and asthma cannot be completely ruled out, and the role of PDLIM4 needs to be interpreted cautiously." (PMID 37809092, 2023).
leukemia (2 papers, 2011 to 2014). A malignant (clonal) hematologic disorder, involving hematopoietic stem cells and characterized by the presence of primitive or atypical myeloid or lymphoid cells in the bone marrow and the blood. "DPYS, NPM2, OSCP1, PDLIM4 and TFAP2E genes were found hypermethylated, and CDKN2B (p15INK4B) homozygously deleted in the K562 leukemia cell line." (PMID 21760961, 2011).
osteoporosis (2 papers, 2019 to 2023). A condition of reduced bone mass, with decreased cortical thickness and a decrease in the number and size of the trabeculae of cancellous bone (but normal chemical composition), resulting in increased fracture incidence. "Certain variants of the PDLIM4 gene have been associated with osteoporosis." (PMID 37047477, 2023). "A previous study of Japanese women has shown that the PDLIM4 (-3333T–>C) genetic variation of the 5′-flanking region is associated with radial BMD, suggesting that it may disrupt the function of PDLIM4 and contribute to osteoporosis." (PMID 30578378, 2019).
bladder cancer (1 paper, 2020). "According to the Kaplan–Meier survival curves by different mRNA expression levels of hub genes of the bladder cancer with grade 3 carcinoma, GSN, PDLIM4, and HTRA1 were identified as prognostic genes (log-rank test: p = 5.796 × 10−5; log-rank test: p = 9.952 × 10−6; log-rank test: p = 0.009244)." (PMID 32640634, 2020).
diabetes (1 paper, 2025). "A diabetes-specific targeted analysis showed negatively enriched Z-disc and contractile gene sets enriched due to the downregulation of CASQ2, peripherin (PRPH), nebulette (NEBL), titin-cap (TCAP), and LIM domain-binding proteins LDB3, PDLIM4, and PDLIM5 (Dataset EV36)." (PMID 40759793, 2025).
Hyperglycemia (1 paper, 2017). An increased concentration of glucose in the blood. "The islet expression of Family with sequence similarity 105, member A (FAM105A) and PDZ and LIM domain 4 (PDLIM4) was associated with both T2D and hyperglycemia." (PMID 28473845, 2017).
malignant glioma (1 paper, 2022). A grade III or grade IV glioma arising from the central nervous system. "Of the 12 overexpressed genes, ABCC3, COL8A1, IBSP and PDPN are reportedly associated with GBM, while CTHRC1, PDLIM4 and MYL9 are associated with high-grade and malignant gliomas, respectively." (PMID 35456975, 2022).
metastatic cancer (1 paper, 2006). A carcinoma which has spread from the original site of growth to another anatomic site. "Examples of these unique genes include Serpine2, which is overexpressed in metastatic cancer; Ctnnb1, Fliih, Pdlim4/Ril, all of which affect migratory behavior of cells; and Gas6, which is a ligand for the Axl oncogene." (PMID 17147824, 2006).
osteosarcoma (1 paper, 2016). A usually aggressive malignant bone-forming mesenchymal neoplasm, predominantly affecting adolescents and young adults. "For example, overexpression of Pdlim4 in osteosarcoma cells causes continuous assembly and collapse of stress fibers, resulting in rapid changes in cell shape, while knockdown of Pdlim1 in BeWo cells leads to loss of stress fibers and focal adhesions." (PMID 27792740, 2016).
thyroid tumor (1 paper, 2025). A benign or malignant neoplasm affecting the thyroid gland. "We found new characteristics of thyroid tumors, such as methylation of TP73, WIF1, and PDLIM4 TSGs, which can contribute to thyroid neoplasia." (PMID 41150811, 2025).
tumor (18 papers, 2011 to 2026). "Hypermethylation of the PDLIM4 gene is also used as a marker for cancer detection because, in prostate cancerous cells, up-regulation of the expression level of mRNA of PDLIM4 and its protein was found, and it acts as a tumor suppressor." (PMID 37858151, 2023). "Numerous studies have shown that hypermethylation of the PDLIM4 gene leads to the development and malignant progression of PC, and functional experiments have confirmed that PDLIM4 can inhibit tumor growth by suppressing PC cell proliferation." (PMID 37894409, 2023). "In contrast, PDLIM4 functions as a tumor suppressor and is hypermethylated and suppressed in PRAD cell lines compared to normal prostate cells." (PMID 35707002, 2022). "PDZ and LIM domain 4 (PDLIM4) is a potential tumour suppressor gene involved in cell growth regulation." (PMID 34923978, 2021). "Otherwise, the expression of PDLIM4 is often downregulated in the advanced tumor stage of cancer tissues and lymph node metastasis." (PMID 32085612, 2020). "PDLIM4, which is up-regulated by Tax-1 and Tax-3, has a tumor suppression function and is repressed by DNA methylation in many cancers." (PMID 22911729, 2012). "Previously, the PDLIM4 gene was identified as a tumour suppressor." (PMID 36936167, 2023). "In addition, the level of two TS proteins, VHL and PDLIM4, was increased in SH-I-14-treated tumor samples." (PMID 29137356, 2017). "However, with increased NF-kB inactivation, DNMT1 activity could be decreased, resulting in hypomethylation of tumor suppressors such as PDLIM4 (PDZ and LIM domain 4) gene." (PMID 34358067, 2021). "For instance, PDLIM4, also known as RIL, is a LIM domain protein that has tumor-suppressor and pro-apoptotic properties." (PMID 21760961, 2011). "Similarly, after their culture with ECs, IL30-overexpressing PCs showed a dramatic upregulation of a wide range of oncogenes, which included CCND2, EGR3, IGFBP5, KLK3, PDLIM4, PTGS1 and SHBG and a few tumor suppressors, such as GPX3, FOXO1, MAX and NKX3-1." (PMID 38087324, 2023).
cancer (10 papers, 2011 to 2026). A tumor composed of atypical neoplastic, often pleomorphic cells that invade other tissues. "A recent report suggests that PDLIM4 is important for inactivation of Src and that epigenetic silencing of PDLIM4 may contribute to aberrant activation of Src in cancer." (PMID 21760961, 2011).
prostate (1 paper, 2019). "Furthermore, the hypermethylation of PDLIM4 could be used as a sensitive molecular tool in the detection of prostate tumorigenesis." (PMID 30578378, 2019).
PDLIM4 also shares sentences with these, for which no sentence is quoted: gastric cancer (2 papers); acute myeloid leukemia (1); breast tumor (1); colon cancer (1); colorectal cancer (1); fracture (1); glioblastoma (1); hepatocellular carcinoma (1); lung adenocarcinoma (1); malaria (1); melanoma (1); neonatal-onset multisystem inflammatory disease (1); prostate tumor (1).